KIF23 (kinesin family member 23)
Diseases named in the same sentence as KIF23 in open-access papers (continued):
Sharing a sentence is not in itself a finding about the gene and the disease.
tumor (64 papers, 2012 to 2026). "This is the case of KIF23, which was a hub gene in M2-tumor-associated macrophages, and it showed a higher expression level in tumor tissues, similarly to YWHAQ and AGRN." (PMID 40136513, 2025). "To investigate the role of risk scores consisting of KIF23 in the GC tumor microenvironment, we evaluated the immune cell score of each GC sample using CIBERSORT, and xCell algorithms." (PMID 37483517, 2023). "We also noted that KIF23 protein expression was significantly associated with tumor site, tumor stage, lymph node metastasis, nerve invasion, and CEA among the 80 patient samples." (PMID 36522719, 2022). "Among the different analysis methods and cancer types, the kinesin family members KIF20A and KIF23 were consistently among the top genes associated with malignant transformation or tumor stage." (PMID 33819271, 2021). "Our results showed that increased expression of ANLN and KIF23 was associated with higher tumor grade." (PMID 34917682, 2021). "Antagonism of KIF23 expression causes cell growth inhibition, and the formation of enlarged cell bodies with binuclear/multinuclear in many tumor cells, probably due to the cell cycle arrest which further caused mitosis failure." (PMID 34017355, 2021). "KIF23, a key regulator of cell division, has been implicated in tumor progression, but its role in ATC remains unclear." (PMID 41675939, 2026). "KIF23 expression level, age, tumor stage and grade were associated with OS in ccRCC patients." (PMID 35478956, 2022). "Furthermore, KIF23 mutation was detected in about half of 38 tested tumor types (20 out of 38 were confirmed with elevated KIF23 expression)." (PMID 34017355, 2021). "Therefore, KIF23 can be used as a tumor-associated antigen, and its overexpression is widely involved in tumor progression." (PMID 33754001, 2021). "The differential expression patterns for the two splice variants of KIF23 suggest that they may have distinct activities in tumor cells." (PMID 26674738, 2015). "However, the differences in the localization, expression, and function for the two splice variants of KIF23 in tumor cells have remained largely unknown so far." (PMID 26674738, 2015). "For instance, overexpression of KIF23 was correlated with tumor invasiveness and poor prognosis of hepatocellular carcinoma." (PMID 41138746, 2025). "The Tumor-4 subcluster had proliferating features and was marked by Mki67 and additional cell cycle genes, such as Kif23 and Ndrg1." (PMID 41332581, 2025). "The IHC results demonstrated markedly higher KIF23 levels in tumor tissues compared with adjacent normal tissues, confirming the upregulation of KIF23 in PTC." (PMID 41138746, 2025). "Numerous studies have demonstrated that KIF23 mRNA and/or protein is overexpressed in NSCLC and SCLC tumours, which are associated with poor prognosis of patients, specifically greater tumour stage, and worse overall and recurrence-free survival." (PMID 40002279, 2025). "Kinesin family member 23 (KIF23) is a kinesin family member that is widely involved in mitosis, and its upregulation is often associated with tumor development." (PMID 40867281, 2025). "For example, SIRT7 has been shown to repress succinylation of KIF23, affecting cell cycle progression and tumor growth." (PMID 40586636, 2025). "As a result, KIF23 has the potential to be exploited as an immunotherapy biomarker and predictor of tumor immunotherapeutic response." (PMID 37483517, 2023). "The KIF23 expression level in tumor tissues was significantly higher than that in adjacent tissues (P < 0.001), and also higher in tumor tissues than in paired adjacent tissues (P < 0.001)." (PMID 37483517, 2023). "We next detected KIF23 expression in 38 paired tumor tissues and in corresponding adjacent tissues from TNBC patients." (PMID 35524313, 2022).
tumor (continued). "Then, functional experiments in vitro and in vivo were performed to investigate the effects of KIF23 on tumor growth and metastasis in TNBC." (PMID 35524313, 2022). "In ccRCC tumor biology, knocking down KIF23 expression in ccRCC cells inhibited the malignant behavior of ccRCC cells." (PMID 35478956, 2022). "KIF23, a member of kinesin proteins, and its role in tumor development has been demonstrated in many tumors, yet its role in ccRCC remains elusive." (PMID 35478956, 2022). "Tumor sizes and weights of KIF23 knockdown group were significantly lower than those of the control group." (PMID 35524313, 2022). "Six genes were up-regulated in the tumor group and high-risk group consisting of SMAD3, CENPA, KIF23, NUSAP1, INCENP, and SMC4." (PMID 36401386, 2022). "The results showed that the expression of RRM2 and KIF23 was significantly up-regulated in HCC tumor tissues compared with adjacent tissues (P < 0.001)." (PMID 34324544, 2021). "CENPF, BUB1, BUB1B, KIF23 and TTK were identified as the key potential genes affecting hypoxia associated tumor stemness in this study." (PMID 33148251, 2020). "In formed tumor tissues, significantly reduced expression of KIF23 was observed after KIF23 knockdown, and the tumors formed in the shRNA-KIF23 group were noninvasive or well-encapsulated tumors." (PMID 32365332, 2020). "Whereafter, the expression of PVT1, miR-15a-5p and KIF23 was detected in removed tumor tissues, and we found the expression of PVT1 and KIF23 was significantly declined, while miR-15a-5p expression was strengthened by qRT-PCR analysis." (PMID 32624708, 2020). "Consistently, the public datasets and our experimental results confirmed that KIF23 was upregulated in GC tissues and that expression of KIF23 was relatively high in advanced tumor tissues." (PMID 32365332, 2020). "Taken together, these results indicate that KIF23 is a potential marker for predicting tumor malignancy and prognosis." (PMID 27013586, 2016). "Next, we performed multivariate Cox regression analysis incorporating KIF23 expression, age, IDH1 mutation and tumor grade." (PMID 27013586, 2016). "We observed a positive correlation of KIF23 expression with a series of tumor oncogenes, driving cell proliferation, mitosis and metastasis, including E2F transcription factor family (E2F1, E2F1, E2F3) and Rhoc." (PMID 27013586, 2016). "In conclusion, we prepared polyclonal antibody specific to KIF23 V1 to distinguish KIF23 V1 from KIF23 V2, and we show for the first time that KIF23 V1 and KIF23 V2 have different localizations in tumor cells." (PMID 26674738, 2015). "Expression of KIF23 protein in tumor cells was assessed by IHC with anti-KIF23 V1 or anti-KIF23 antibodies." (PMID 26674738, 2015). "Immunohistochemical staining of HCC tissues with anti-KIF23 V1 or anti-KIF23 antibodies indicated that tumor tissues were significant heterogeneity with some tumor cells expressing high levels of KIF23 V1 or V2 protein while being undetectable in others." (PMID 26674738, 2015). "The aim of our study was to investigate the role of KIF23 in tumor growth." (PMID 38514510, 2024). "In addition, the correlation between KIF23 and immunological marker genes suggests that KIF23 can control immune cell infiltration within the tumor microenvironment (TME) in GC." (PMID 37483517, 2023). "The expression of KIF23 was higher in the tumor tissues compared to that in adjacent tissues." (PMID 37483517, 2023). "In addition, KIF23 is a potential key gene regulating hypoxia-induced tumor cell stemness in the immune microenvironment of lung tumors." (PMID 36408131, 2022). "Moreover, the results of immunohistochemistry staining showed that KIF23 expression were higher in tumor specimens." (PMID 35478956, 2022). "The results indicated knockdown of KIF23 alleviated tumor growth and metastasis in vivo." (PMID 35524313, 2022). "In ccRCC, we found the expression of KIF23 was significantly elevated in tumor tissues." (PMID 35478956, 2022).
tumor (continued). "As anticipated, the protein level of KIF23 was also increased in ccRCC tumor tissues." (PMID 35478956, 2022). "Thus, we observed higher KIF23 mRNA levels in tumor tissues as well as a positive correlation between KIF23 mRNA expression and NAT10, consistent with TCGA or GEO datasets (GSE40967)." (PMID 36522719, 2022). "The results showed that KIF23 expression was positively correlated with tumor grade." (PMID 34017355, 2021). "The expression level of KIF23 was significantly related with higher tumor grade (P < 0.001)." (PMID 33747931, 2021). "KIF23 was highly expressed in both normal liver tissues and tumor tissues." (PMID 34324544, 2021). "Besides, KIF23 knockdown attenuated proliferation, migration and invasion but promoted apoptosis of PCa cells, implying that KIF23 was a tumor promoter in PCa." (PMID 32624708, 2020). "Following this second hypothesis, we computationally found reliable interactions between UCA1 and the 3′-UTRs of ANLN, BIRC5, IPO7, KIF2A, and KIF23 that overlapped several miRNA-binding sites of tumor-suppressor miRNAs." (PMID 30195762, 2018). "KIF23 expression was positively correlated with tumor grade (P<0.01)." (PMID 27013586, 2016). "Of course, in order to achieve a better understanding of the mechanism of KIF23 V1 expression in carcinogenesis and progression of cancer in patients with HCC, further studies on the biological functions of KIF23 V1 and V2 as well as their relationships in tumor cells are necessary." (PMID 26674738, 2015). "However, all the commercial anti-KIF23 antibodies recognize both KIF23V1 and V2, thus little is known about the expressions and functions of each individual variant in tumor cells so far." (PMID 26674738, 2015). "However, applying anti-KIF23 antibody for IHC staining, positive staining was predominantly observed in the cytoplasm of tumor cells, suggesting that KIF23 V2 localized in the cytoplasm of HCC cells." (PMID 26674738, 2015). "In addition, these CENPF-related genes exhibited the expression differences between normal and tumor tissues: the expression of TOP2A or KIF23 was significantly upregulated in LPS, while that of BAG1,PNPLA2, CRYL1 or GRN was significantly downregulated in LPS or MRCLPS compared to normal tissues." (PMID 37108172, 2023). "Taken together, we explored the mechanism underlying NAT10-mediated ac4C modification in regulating CRC progression and observed that NAT10 could acetylate KIF23 mRNA, resulting in the activation of the Wnt/β-catenin pathway and leading to tumor proliferation and metastasis." (PMID 36522719, 2022). "However, to date, only few studies have been reported on the expressions of KIF23 in tumor cells." (PMID 26674738, 2015). "KIF11, KIF23, and KIF14 are motor proteins involved in mitosis and intracellular transport that can influence tumor growth and spread, possibly affecting recruitment and localization of immune cells within TME." (PMID 39083127, 2024). "The expression levels of KIF2C, CENPA, CDC20, UBE2C, ESPL1, KIF23, and PLK1 were significantly higher in the tumor tissues of patients with a HOST-response compared to those without a HOST-response." (PMID 39201599, 2024). "Kinesin family member 23 (KIF23), an index of tumor proliferation, can serve as a prognostic marker in numerous tumors." (PMID 37483517, 2023). "In conclusion, we found that CENPF, BUB1, BUB1B, KIF23 and TTK were potential key genes involved in regulating hypoxia induced tumor cell stemness." (PMID 33148251, 2020). "DEmRNAs, including ATAD2, KIF23, MCM4, CCNB1, and CCNE1, are highly expressed in LUAD than in corresponding non-tumor tissues." (PMID 33042838, 2020).
tumor (continued). "Using the prepared antibody specific to KIF23 V1, we found the distinct expression patterns of KIF23 V1 and V2 protein in HCC tumor tissues." (PMID 26674738, 2015). "However, the staining intensity or the range of positive areas of CEP55, KIF23, MYBL2, and RACGAP1 was higher in tumor samples (medium or high levels) than in non-tumor tissue." (PMID 34093635, 2021). "Many of the key regulators in the canonical oncogenic (tan) module were involved in the processes leading to tumor cell proliferation and survival (TPX2, NCAPH, KIF11, NUSAP1, KIF23, MCM10) but most of them have not been associated with pediatric tumors." (PMID 31988326, 2020). "FBXL19-AS1 might act as the inducible endogenous RNA of hsa-miR-20b-5p to influence the expression of BTG3, KIF23, RBBP7, and TRIM37 and regulate tumorigenesis, Wnt/β-catenin pathway, tumor metastasis as well as apoptosis." (PMID 33344260, 2020). "Using the antibody specific to KIF23 V1 for immunohistochemical staining of HCC tissues, we also found that KIF23 V1 was predominantly localized in nucleus of tumor cells, which was quite different from the positive staining in cytoplasm using commercial anti-KIF23 antibody." (PMID 26674738, 2015). "KIF23 V1 expression (negative vs. positive; P = 0.0097), tumor size (≤5 cm vs. >5 cm; P = 0.0186), TNM stage (I, II vs. III, IV; P = 0.0040), were identified as parameters significantly influencing survival." (PMID 26674738, 2015). "Furthermore, knockdown of KIF23 expression significantly suppressed the in vivo tumorigenicity of SGC-7901 and MGC-803 cells after subcutaneous injection of the cells into nude mice, as demonstrated by reduced tumor size and weight." (PMID 32365332, 2020). "Overall, we identified CENPF, BUB1, BUB1B, KIF23 and TTK as potentially key genes involved in regulating hypoxia-induced tumor cell stemness, and found that AC079160.1-miR-539-5p-CENPF axis may be involved in regulating hypoxia induced tumor cell stemness in LUAD." (PMID 33148251, 2020). "We speculate that KIF23 V1 may be involved in hepatocarcinogenesis, however, once the tumor is formed, it may play a negative role during the progression of cancer." (PMID 26674738, 2015).
cancer (52 papers, 2015 to 2026). A tumor composed of atypical neoplastic, often pleomorphic cells that invade other tissues. "Elevated KIF23 expression has been linked to poorer cancer outcomes, and it is correlated with immune cell permeation and reaction to immunotherapeutic treatments." (PMID 40236649, 2025). "In recent years, abnormal KIF23 expression has been linked to the initiation and progression of various cancers." (PMID 41138746, 2025). "Previous studies have also reported that KIF23 is associated with cell proliferation, and regulates the cell cycle in many types of cancers." (PMID 37483517, 2023). "Previous study showed that in the tumors with up-regulated KIF23 expression, DNA mutation of KIF23 was detected in nearly half of tested human cancer types, and CNAs of KIF23 showed gain in 30% of tested tumors." (PMID 34017355, 2021). "Besides, KIF23 is significantly up-regulated and associated with poor prognosis in different kinds of cancers." (PMID 38360598, 2024). "Moving to KIF23, it also stimulates cell proliferation and is associated with cancer progression." (PMID 37175004, 2023). "Abnormal expression of KIF23 can cause tumorigenesis and cancer development." (PMID 32548103, 2020). "In recent years, the dysregulation of KIF23 expression was found in the development and progression of various human cancers." (PMID 41138746, 2025). "Recent research indicates that KIF23 plays an important role in the proliferation and migration of cancer cells." (PMID 38360598, 2024). "The downstream of DEPDC1B, KIF23, is a member of kinesin motor protein involved in the regulation of cytokinesis and acts as an important regulator in cancer biology." (PMID 34983303, 2022). "These genes, such as ANXA1, SMC2, KIF23, and DDX5, are primarily associated with cancer cell proliferation, metastasis, and poor prognosis." (PMID 35184675, 2022). "Reportedly, KIF23 is the regulator of the central spindle assembly and is involved in the malignant behavior of several cancers via the Wnt/β-catenin signaling pathway." (PMID 36522719, 2022). "Coexpression analysis revealed that KIF11, KIF18B, KIF23, and MKI67 were positively associated with the expression of IQGAP3 in all cancer types presented in the heatmap." (PMID 36164370, 2022). "The HT29 line-derived EV proteins ST14, and KIF23 were annotated against the KEGG database as belonging to the signaling pathway “MicroRNAs in cancer”." (PMID 32916986, 2020). "Although KIF23 has been studied in GC, little was previously known regarding the mechanisms by which KIF23 promotes cancer cell growth." (PMID 32365332, 2020). "Dysfunction of KIF23 results in incomplete cytokinesis and formation of binucleated or multinucleated cells, which are hallmarks of cancer." (PMID 32365332, 2020). "KIF23 was reported to be up-regulated in numerous cancers, leading to the accelerative cell proliferation, migration, poor prognostic and other harmful acts." (PMID 32624708, 2020). "The disfunction of KIF23 resulted in incomplete cytokinesis and formed binucleated or multinucleated cells, which have been considered as the hallmarks of the cancer cells." (PMID 26674738, 2015). "KIF18A and KIF23 are members of the kinesin family and were overexpressed in many malignant tumors." (PMID 40255404, 2025). "Similarly, KIF23 promotes the proliferation, migration, and invasion of various tumors in vitro and in vivo, playing a tumorigenic role in cancer progression." (PMID 38360598, 2024). "Consequently, these findings indicate that KIF23 plays a crucial role in cancer initiation and progression, offering novel insights and potential therapeutic options for cancer treatment." (PMID 38514510, 2024). "This could provide a reference for further study to explore the specific mechanism of KIF23 in ATC or other cancers." (PMID 38360598, 2024).